PANX1 (pannexin 1)
Diseases named in the same sentence as PANX1 in open-access papers (continued):
Sharing a sentence is not in itself a finding about the gene and the disease.
cancer (continued). "Knockdown of PANX1 significantly reduced the release of ATP and decreased the cancer immunogenicity that promotes dendritic cell maturation and proinflammatory cytokine production, resulting in decreased T-cell-mediated cytotoxicity." (PMID 38195677, 2024). "TNFα promoted PANX1 cleavage via a caspase 8/3-dependent pathway to enhance cancer cell immunogenicity, leading to dendritic cell maturation and T-cell activation." (PMID 38195677, 2024). "Here, we found that the addition of TNFα increased the immunogenicity of OXP-treated cancer cells via the PANX1-ATP-P2RX7 axis." (PMID 38195677, 2024). "PANX11-89 along with wild-type PANX-1 promotes gain of function of channel activity, an increased ATP release, and resistance of cancer cells to mechanical deformation." (PMID 36741002, 2023). "Cancer cells release ATP from pannexin-1 (PANX1) hemichannels, P2X7R, or by cellular lysis and can activate either P2 receptor." (PMID 36741002, 2023). "Uncontrolled activation of Panx1 channels and/or aberrant iCa2+ levels result in enhanced metastasis and drug tolerance of cancer cells." (PMID 37385076, 2023). "NK-LAAO treatment amplifies interleukin (IL)-6 expression via the pannexin 1 (Panx1)-directed intracellular calcium (iCa2+) signaling pathway to confer adaptive and aggressive phenotypes on cancer cells." (PMID 37385076, 2023). "Panx1 functions as a mediator of pro-inflammatory cytokines release and cancer cell metastasis and survival." (PMID 37385076, 2023). "The beneficial or detrimental role of connexin and pannexin-1 in different cancer types remains controversial." (PMID 36833374, 2023). "The Panx-1-dependent release of nucleotides contributes to their various functions, including cell clearance and inflammation, cancer progression, blood pressure regulation, metabolic defects, and neurological disorders." (PMID 36833374, 2023). "In most cancer types, Panx1 expression negatively correlates with disease onset or progression, but some exceptions have been reported." (PMID 36833374, 2023). "NK-LAAO treatment activates the Panx1/iCa2+ signaling pathway to potentiate cancer cells to induce IL-6 expression, leading to cytotoxic tolerance and acquisition of the metastatic phenotype." (PMID 37385076, 2023). "Apoptotic cells promote neutrophil accumulation and the formation of neutrophil extracellular traps (NETs) in a pannexin 1 (Panx1) channel-dependent manner through the release of spermidine, contributing to cancer cell immune escape mechanisms." (PMID 37296983, 2023). "We found a difference in the expression of Cx37 and Panx1 in cancer and adjacent normal laryngeal mucosa and between different histological grades of cancer." (PMID 36833374, 2023). "Collectively, our study urges caution when using svLAAOs in cancer treatment and identifies the Panx1/iCa2+/IL-6 axis as a therapeutic target for improving the effectiveness of svLAAOs-based anticancer therapies." (PMID 37385076, 2023). "Further, PANX1 is activated when cancer cells are subjected to deformation as they travel along the microvasculature, which contributes to cancer metastasis." (PMID 35163442, 2022). "Hypoxic stress induces cancer cells’ ATP to release through pannexin 1 PANX-1 channels and exocytosis of adenosine and promotes the accumulation of adenosine in the extracellular space of hypoxic tumors." (PMID 36176756, 2022). "Consistently, when the PANX1 channel is inhibited in cancer cells, these cells still survive under hypotonic stress in the presence of extracellular ATP." (PMID 35163442, 2022).
cancer (continued). "Using the cBioPortal web tool, we investigated PANX1 gene alterations in 33 cancer types and 10,953 patients." (PMID 34796785, 2021). "In this study, using an online database, we conducted a pan-cancer analysis to investigate the expression profiles and prognostic landscape of PANX1." (PMID 34796785, 2021). "During the past years, increasing interest have grown on study PANX1 role during mesenchymal migration, particularly in the context of cancer progression." (PMID 34975840, 2021). "Another significant finding from this study is that PANX1 expression correlates with certain immunomodulators in a variety of cancers." (PMID 34796785, 2021). "Based on the median value of PANX1 mRNA in individual tumors, cancer patients were classified into high and low expression groups." (PMID 34796785, 2021). "PANX1 was shown to be positively associated with some immune inhibitors such as CD274, PDCD1LG2, and TGFBR1 in a variety of cancers." (PMID 34796785, 2021). "Because ATP is a well-known immunomodulator, we further investigated the relationship between PANX1 expression and immunomodulators in human cancers." (PMID 34796785, 2021). "Altogether, these data supports the notion that PANX1 is a negative regulator tumor suppressor factor in cancer cells." (PMID 34975840, 2021). "We and others have previously shown that ivermectin is a positive allosteric modulator of purinergic signaling and the ATP/P2X4/P2X7/Pannexin-1 axis which operates in both cancer and immune cells." (PMID 33654071, 2021). "According to multiple algorithms, the relationships between PANX1 expression and B cells in various cancers were complex and diverse." (PMID 34796785, 2021). "According to the gene expression and prognosis analysis, we found that the expression status and predicted values of PANX1 were inconsistent in different cancers across different databases." (PMID 34796785, 2021). "Firstly, the study into the role of PANX1 in cancers relied on publicly available databases, and the predicted results were not validated by experimental methods." (PMID 34796785, 2021). "Oncomine and GEPIA 2.0 databases were used to investigate the levels of PANX1 mRNA expression levels in various human cancers and adjacent normal tissues." (PMID 34796785, 2021). "A mechanism that has gained attention in cancer is ATP release through pannexin-1 channel (PANX1), since a truncated PANX1 protein (PANX11−89) is significantly enriched in highly metastatic human cancer cell lines." (PMID 32635260, 2020). "Our results suggest that FUS can directly stimulate ER localized PANX1 in invasive PC-3 cancer cells to generate Ca2+ release from intracellular ER stores, independently of extracellular Ca2+ entry." (PMID 32656213, 2020). "Here, we identify the membrane channel PANNEXIN1 (PANX1) as a mediator for activation of calcium signaling in invasive cancer cells." (PMID 32656213, 2020). "Knockdown of PANX1 decreases calcium signaling in invasive cells, while PANX1 overexpression enhances calcium elevations in non-invasive cancer cells." (PMID 32656213, 2020). "In this study we establish a new role for the mechanosensitive PANX1 hemichannel in mediating Ca2+ signaling in invasive cancer cells." (PMID 32656213, 2020). "The chromosome 9 QTL interval contains several genes involved in inflammation and/or in cancer such as Caspase 1 (Casp1) and pannexin 1 (Panx1), involved in the release of mature inflammatory IL-1β." (PMID 31049358, 2019). "For most cancer types, Panx1 expression positively correlates with the onset or progression of the disease." (PMID 30654593, 2019). "In tissues, upregulation or amplification of PANX1 was reported in human biopsies from most cancer types according to the analysis of cross-cancer alterations in the 89 cancer studies included on the cBioPortal.org for Cancer Genomics." (PMID 27229305, 2016).
cancer (continued). "Panx1 expression was also more abundant in patients with cancer on the right side of the colon compared to those who had it on the left side, suggesting the existence of molecular subtypes in cancer of the right colon." (PMID 40227837, 2025). "Overexpression of Panx1 in malignant glioma cells hindered C6 cell proliferation [17308093]." (PMID 40909173, 2025). "Precise control of purinergic signalling via PANX1 is critical in many diverse cell types, including maintaining neural stem cell populations, regulating the development of immature neurons, and tumorigenicity and metastasis of several cancers." (PMID 41250870, 2025). "We will particularly emphasize the recent advances in pharmacological targeting of Panx channels using clinically approved drugs (e.g., CBX, PBN) and synthetic peptide inhibitor targeting Panx1 W74 to Y83 (10Panx), and evaluate their therapeutic potential in inflammation and cancer." (PMID 40909173, 2025). "Clarifying these aspects may be key to targeting Panx1 therapeutically in inflammation, neurodegeneration, or cancer." (PMID 40978734, 2025). "Additionally, it examines the therapeutic perspectives related to Panx1 modulation, highlighting its significance in inflammatory diseases and cancer." (PMID 40978734, 2025). "We further evaluated whether PANX1-mediated ATP release influences cancer immunogenicity to promote DC maturation." (PMID 38195677, 2024). "Low PANX1 expression in cancer cells resulted in the release of lower ATP levels in response to chemotherapeutic drug treatment and immunogenicity that was insufficient for promoting dendritic cell maturation, proinflammatory cytokine release, and T-cell-mediated killing in vitro." (PMID 38195677, 2024). "According to our results, the expression of Cx37, Cx40, and Panx-1 might be abolished in less differentiated cancer." (PMID 36833374, 2023). "•NK-LAAO treatment enables cancer cells to produce IL-6 via the Panx1/iCa2+ pathway." (PMID 37385076, 2023). "Moreover, Panx1 mRNA levels are inversely correlated with the OS of cancer patients across the TCGA Pan-Cancer dataset." (PMID 37696858, 2023). "Panx1 may be involved in the development of cancer in humans, although the exact pathophysiological mechanism is still unknown." (PMID 36833374, 2023). "PANX1/Panx1 expression is tightly regulated in the context of differentiation and development in various cell and tissue types 10-15 and are altered in a variety of diseases including cancer 11, 16-19." (PMID 37056395, 2023). "According to studies, connexins and Panx1 are involved in the development of many human cancers." (PMID 36833374, 2023). "Moreover, focused ultrasound (FUS) can stimulate ER-localized mechanosensitive PANX1 and result in the release of Ca2+ from the ER in invasive cancer cells." (PMID 35163442, 2022). "Only a few studies have been conducted to determine the PANX1’s prognostic power in cancer." (PMID 34796785, 2021). "PANX1 plays an important role in normal physiological processes, including skin development and wound healing as well as in pathophysiological conditions and metabolic disorders, such as Alzheimer’s disease, diabetes, inflammation, and cancer." (PMID 33647315, 2021). "In this study, we used the cBioPortal website to analyze PANX1 gene alterations in 33 cancer types." (PMID 34796785, 2021). "PANX1 expression was higher in pan-cancer samples than in normal tissues." (PMID 34796785, 2021). "In this study, we investigated PANX1 expression levels and prognostic landscape in various cancer." (PMID 34796785, 2021). "The mechanism by which PANX1 affects the immune response to cancer is complex." (PMID 34796785, 2021). "We analyzed the expression of PANX1 in human pan-cancer in the Oncomine and GEPIA2.0 databases." (PMID 34796785, 2021).
cancer (continued). "We found that PANX1 modulates the expression of genes involved in numerous BPs characteristic of cancer including, in descending order of significance, cell–cell adhesion, extracellular matrix disassembly, regulation of apoptosis, migration, and cellular morphology." (PMID 33564071, 2021). "As a result, 179 (1.6%) of the 10,953 cancer patients had PANX1 gene alterations." (PMID 34796785, 2021). "The results indicated that PANX1 was overexpressed in most cancers compared to normal tissues." (PMID 34796785, 2021). "In addition, we recently showed that ultrasound-induced ATP release was reduced significantly when the pannexin 1 hemichannel was either inhibited or knocked down in the prostate PC-3 cancer cells." (PMID 32375298, 2020). "Recent studies show that Panx1 is involved in the development of many human cancers." (PMID 31737105, 2019). "This controversy in the role of PANX1 during cancer progression could be due to differences in the type or stage of cancer." (PMID 31817827, 2019). "PANX1 is involved in multiple disease states, including cancer." (PMID 30654593, 2019). "Only recently, however, has Panx1 been studied in the context of cancer." (PMID 30459312, 2018). "These are tools that could be exploited as different ways of inhibiting the Panx1 channel that may prove useful as novel treatments in the fight against different cancers." (PMID 27229305, 2016). "Our current knowledge of Panx1 function in cancer is limited." (PMID 27229305, 2016). "An unexpected side effect of this Panx1 expression, other than its potential role in cancer progression, is the possibility that Panx1 channels in the presence of different chemotherapeutic drugs, can actually be exploited to enhance cancer cell death." (PMID 27229305, 2016). "Panx1 is commonly expressed and even upregulated in many cancer cells." (PMID 27229305, 2016). "The role of PANX1 in ATP-mediated macropinocytosis could be particularly important for disease states implicating PANX1, such as cancer, where ATP can act as a purinergic regulator of cell growth/metastasis and as a supplementary energy source following internalization." (PMID 41250870, 2025). "Therefore, the aim of this study was to analyze the expression of Cxs and Panx1 in cancer and adjacent normal mucosa and vimentin, an indirect marker of epithelial–mesenchymal transition in LSCC, and to correlate the results with pathological parameters, pathological stage and clinical outcome." (PMID 36833374, 2023). "Interestingly, dichotomic contribution of PANX1 on cancer cell migration has been reported." (PMID 34975840, 2021). "However, research on the role of PANX1 in human pan-cancer is limited." (PMID 34796785, 2021). "However, in other cancer cell lines, PANX1 acts as a pro-migration factor as we discuss below." (PMID 34975840, 2021). "The findings suggested that PANX1 may play an important in tumorigenesis and cancer progression." (PMID 34796785, 2021). "Whether cancer cells take up ATP from PANX1 channels in the in vivo setting is unclear at present." (PMID 30814334, 2019). "Pannexin 1 (PANX1) subunits form oligomeric plasma membrane channels that mediate nucleotide release for purinergic signalling, which is involved in diverse physiological processes such as apoptosis, inflammation, blood pressure regulation, and cancer progression and metastasis." (PMID 28134257, 2017). "It is therefore possible that Panx1 expression may be needed at early stages of development, but needs to be down-regulated in the adult to avoid the negative effects of its expression in pathological states including cancer." (PMID 27229305, 2016). "However, the Cancer Genome Atlas also reports some examples of PANX1 deletions present in human biopsies, indicating that Panx1 expression could be regulated differently in specific cancer types." (PMID 27229305, 2016).
cancer (continued). "PANX1 deletion by CRISPR/Cas9 editing and PANX1 channel inhibition via probenecid (PBN) and spironolactone (SPL) reduces SCC‐13 cancer cell properties of SCC‐13 such as growth and migration." (PMID 39560179, 2025). "ATP is released through the PANX1 channel and a truncated PANX1 protein (PANX11-89) is overexpressed in metastatic human cancer cell lines." (PMID 36741002, 2023). "Therefore, PANX1 channels may prove to be a therapeutic target for cancer metastasis." (PMID 35163442, 2022). "It has been reported that PANX1, ABC, CALHM1, VRACs, and MACs can regulate TME via ATP release channel modulation in order to exert therapeutic effects against cancer." (PMID 36291937, 2022). "Therefore, PANX1 may have a wide variety of biological effects on cancer development." (PMID 34796785, 2021). "However, the roles of PANX1 in different cancers remain unclear." (PMID 34796785, 2021). "This is a newly described role of PANX1 as a regulator of calcium ion exchange between the ER and cytoplasm, suggesting a new working model of how FUS interacts with cancer cells to initiate and propagate Ca2+ signaling." (PMID 32656213, 2020). "The expression of Cx37, Cx40, Panx-1, and vimentin differed significantly between the epithelium of normal laryngeal mucosa and the atypical epithelial cells of LSCC and was related to the histological grade and biological behavior of the cancer." (PMID 36833374, 2023). "PANX1 expressions were found to be positively correlated with a variety of immune infiltrating cells, including neutrophils, CAF, macrophages, MDSC, and monocytes in various cancers, such as PAAD, COAD, LUAD, READ, and UVM." (PMID 34796785, 2021). "The resulting heatmap showed that in the majority of malignancies, TILs were significantly correlated with multiple representative ICD mediators, such as CALR, LRP1, ANXA1, FPR1, TLR3, IFNAR1, PANX1, and P2RX7." (PMID 33299118, 2020). "There are indeed several reports demonstrating increased levels of Panx1 expression in cancer as compared to non-cancer normal tissue." (PMID 30823688, 2019). "It is possible that Panx1 expression is necessary in early development, but needs to be downregulated in adulthood to avoid the negative effects on pathological conditions, including cancer." (PMID 36833374, 2023). "However, the majority of published reports, with three notable exceptions indicate that amplification or upregulation of Panx1 is prevalent in cancer cell lines and tumors compared to normal tissues." (PMID 27229305, 2016). "Then, we describe PANX1 and PANX3 contribution to migration of non-immune cells, such as astrocytes, skin cells, and cancer cells, as well as the few available evidence for the PANX2 and its putative role during cell migration." (PMID 34975840, 2021).